TLR3 (toll like receptor 3)
Diseases named in the same sentence as TLR3 in open-access papers (continued):
Sharing a sentence is not in itself a finding about the gene and the disease.
tumor (continued). "TLR3 and TLR7 identification of viral-based PAMPs inside the tumor microenvironment is thought to initiate antitumor immunity following intratumoral FluVx therapy." (PMID 38476365, 2024). "We found that macrophages in the tumor-containing lymph nodes expressed significantly higher levels of TLR3 and TRAF6 compared to those in the tumor-free lymph nodes." (PMID 38719996, 2024). "TLR3-activation by extracellular vesicle-delivered TRPM8 mRNA triggers aseptic inflammation in the prostate epithelium, promoting tumor suppression by NK cells." (PMID 38316991, 2024). "Consistently, exogenous dsRNA participates in driving Type I IFN induction via targeting RNA-sensing PRR pathways, including RIG-I/MDA5-IPS-1, TLR7-MyD88 and TLR3-TICAM-1 in dendritic cell subset, so as to evoke and amplify CD8+ T cell anti-tumor immunity." (PMID 37138885, 2023). "Considering that TLR3 agonists are promising in clinical treatment as immunoadjuvants, our results may provide guidance for developing novel immunotherapy strategies for MIBC patients with FGFR3 mutations and promoting individualized tumor immunotherapy in the future." (PMID 37283287, 2023). "TLR-3, in the context of both IAV infection and the tumor microenvironment, has a multifaceted role in disease progression and protection against disease pathogenesis." (PMID 37974615, 2023). "PCSCs are responsible for tumor initiation, growth, and relapse in prostate cancer; consequently, TLR3 activation-based immunotherapy using polyinosinic:polycytidylic acid could be a good option for treatment, as it generates apoptosis and an inflammatory response in tumor cells." (PMID 36969009, 2023). "Our results confirm the therapeutic potential of inducing TLR3, since its triggering by IFN-1, and its subsequent activation by dsRNA effectively lead to OS and RMS tumor cell death in vitro and in vivo." (PMID 37414800, 2023). "Anthracyclines, a type of chemotherapy drug, produce type I interferon (IFN) after activating the endosomal pattern recognition receptor Toll-like receptor 3 (TLR3), which binds to IFN-α and IFN-β receptors (IFNAR) on tumor cells." (PMID 37781382, 2023). "TLR3 is also frequently expressed by HNSCC cells, fresh tumor specimens and most HNSCC cell lines propagated in vitro." (PMID 37894949, 2023). "Melanoma-derived EVs entered DCs and activated the TLR3-TRIF signaling to increase Treg production and tumor growth." (PMID 38139035, 2023). "It has been reported that TLR3/TICAM1 signaling is involved in tumor cell RIP3-dependent necroptosis, which contributes to immune effector-mediated tumor elimination." (PMID 36936916, 2023). "The combination of a TLR3 and TLR8 agonist repolarizes TAMs into pro-inflammatory macrophages, reduces tumor growth and increases T cell infiltration into tumors." (PMID 37143666, 2023). "A clinical trial showed that using an advanced form of TLR3 agonist (Poly-ICLC) promotes cancer cell death and inhibits metastasis by activating several cancer suppressors and rebuilding an immunosuppressive tumor microenvironment." (PMID 37112730, 2023). "Disruption of LSD1 catalytic activity stimulates a TLR3- and MDA5-dependent anti-tumor T cell immunity." (PMID 37454216, 2023). "However, we cannot formally exclude the possibility that other necrotic biomolecules are involved in TLR3 activation, especially when the effects on reporter cells are only slightly reduced by RNAse treatment, for example, for the necrotic fluid from the C17 xenografted tumor." (PMID 37894949, 2023). "TLR9 activation is similar to TLR3/ TLR7/TLR8 activation and results in increased expression levels of costimulatory molecules such as TRAIL, which can induce tumor cell death, and CCR7, which promotes trafficking of APCs to lymph nodes." (PMID 37112730, 2023). "MSCs that have been primed with TLR4 are referred to as MSC1 and display an antitumorigenic effect, while MSCs that have been primed with TLR3 are known as MSC2 and have a tumor-supportive role." (PMID 37849741, 2023).
tumor (continued). "DCs produce the Th1-type cytokines IFN-β and IL-12 via the TLR3-TICAM-1 pathway, which contributes to the induction of anti-tumor immunity in functional cytotoxic T lymphocyte." (PMID 36365103, 2022). "Analysis of the methylation status of necroptosis-related regulators between tumor and normal samples from 14 TCGA cancer types showed that RIPK3 and TLR3 exhibited DNA hypermethylation in multiple tumors." (PMID 35748782, 2022). "FASLG, TNFRSF1B, GATA3, TARDBP, ZBP1, TNFRSF21, and TLR3 are mainly expressed in multiple immune cell types, and immune cells have a role in TME to inhibit tumor progression." (PMID 35899194, 2022). "Nanoparticle complexes comprising TLR3 and TLR7 agonists poly(I:C) and imiquimod, respectively, were demonstrated to achieve complete tumor rejection in a B16 melanoma model." (PMID 35740589, 2022). "The expression and function of TLR3 in KIRC, LGG and PAAD were closely related to tumor immune microenvironment." (PMID 36419829, 2022). "It's worth noting that TLR1, TLR2, TLR3, TLR7, TLR8, and TLR9 were adversely connected with RNAss in the majority of cancers, but favourably correlated with RNAss in a very small number of tumours (KIRC, MESO, LAML, CHOL, KICH and THYM)." (PMID 35801728, 2022). "Previous studies have shown that multiple PRRs (TLR2, TLR3, TLR4, TLR7, TLR8 and RIG‐1) in stromal cells recognise tumour cell‐derived EVs and participate in tumour metastasis." (PMID 36068649, 2022). "This synthetic dsRNA mimetic stimulates TLR3 and MDA5, affects IFN-I and IL-15 production, enhances T-cell infiltration into tumor parenchyma, and serves as a strong adjuvant for peptide cancer vaccines." (PMID 36365103, 2022). "Synergistic immune activation with two chemical molecules: Poly(I:C)—a TLR3 targeted agent—and TLR2/4 inducer-BCG led to tumor suppression and the generation of a long-lasting protective immunity in the MBT-2 murine high-grade bladder cancer model." (PMID 35745800, 2022). "Dendritic cells stimulated with TLR3 and TLR7 agonists were found to upregulate ERK signaling, likely contributing to the enhanced dendritic cell activation and anti-tumor T-cell responses observed in CT26 tumors." (PMID 35740589, 2022). "TLR3-TICAM1 pathway can mediate the formation of mature myeloid dendritic cells and render tumor-protecting macrophages to acquire tumoricidal properties." (PMID 35933370, 2022). "TLR3 agonist poly-ICIC and TLR7/8 agonist Resiquimod have been combined with tumor vaccines in the treatment of melanoma (NCT02126579) and advanced tumors refractory to conventional treatment (NCT00948961)." (PMID 36479129, 2022). "We then evaluated the expressions of all TLRs in KIRC tumor tissues by GEPIA and found that TLR3 was particularly highly expressed in KIRC, followed by TLR4 and TLR2, which was consistent with the results of UALCAN database." (PMID 35127830, 2022). "For example, Poly I:C (polyionisic:polycytidylic acid), a synthetic analog of viral dsRNA, induces TLR3/RIP3-dependent necroptosis in colorectal cancer and inhibits tumor growth by the activation of dendritic cells (DC)-mediated anti-tumor activity in vivo." (PMID 36361505, 2022). "Coculture of DCs with tumor-derived EV (TEV) induced the internalization of CD300a and the incorporation of EVs into endosomes, in which CD300a inhibited TEV-mediated TLR3–TRIF signaling for activation of the IFN-β-Treg cells axis." (PMID 34751648, 2021). "In genotoxic chemotherapy with anthracyclines, TLR3 activation in tumor cells has been shown to largely contribute to IFN-I responses and tumor elimination after chemotherapy." (PMID 34925363, 2021). "In KIRC, the results suggested that the mRNA levels of TLR1, TLR2, TLR3, TLR4, TLR7, and TLR8 were elevated in tumour tissues compared with normal kidney tissues." (PMID 34531911, 2021).
tumor (continued). "DaRT used in combination with the TLR9 agonist CpG, TLR3 agonist, poly I:C, or with the TLR1/2 agonist XS15, retarded tumor growth and increased tumor-rejection rates, compared with DaRT alone." (PMID 33503958, 2021). "In this study, we have shown that the combination of immune checkpoint blockade with PLGA particle vaccine containing TLR3/RIG-I ligand Riboxxim and tumor antigen shows a synergistic efficacy in suppression of tumor growth." (PMID 34006895, 2021). "A significant correlation was obtained between TLR3 expression and most of the immune biomarkers in KIRC after tumour purity modulation." (PMID 34531911, 2021). "The results indicated that TLR3 protein expression was increased in patients with KIRC compared with the healthy controls in subgroup analyses based on race, gender, age, weight, tumour grade, and cancer stages (all p < 0.05)." (PMID 34531911, 2021). "We evaluate BCG intratumoral treatment in a subcutaneous MB49 tumor model using different knockout (KO) mice (STING−/−, cGAS−/−, TLR2−/−, TLR3−/−, TLR4−/−, TLR7−/−, TLR9−/−, TLR3/7/9−/−, MyD88−/−, IL-1R−/−, Caspase1/11−/−, Gasdermin-D−/− and IFNAR−/−)." (PMID 34341449, 2021). "Taken together, these data suggest that CD300a inhibits the TLR3–TRIF signaling pathway for IFN-β production at the endosomes in DCs, resulting in the suppression of Treg cell activation and tumor development." (PMID 34751648, 2021). "The expression of TLR1, TLR3, TLR5, TLR6, TLR7, TLR8, and TLR10 show significantly decreasing trends from normal tissues to surrounding tumor tissues and to tumor tissues." (PMID 34141706, 2021). "Previous studies indicated that TLR3 signaling preferentially activates the apoptotic pathway in HCC and other tumor cells." (PMID 33173017, 2020). "This reported that the tumor suppressive and apoptotic effect of TLR3 is achieved predominantly by induction of type I IFN and activation of effector cells, when TLR3 is located within the endosomal compartment." (PMID 33072559, 2020). "While mice treated with either CD40 or TLR3 agonist responded with modest tumor growth delay and increased survival, combined TLR3/CD40 stimulation resulted in superior tumor control and survival in all three tumor models." (PMID 33110069, 2020). "Poly-ICLC stimulates the Th1-polarizing dendritic cells and microglia-expressed toll-like receptor 3 (TLR3), resulting in the anti-tumor immune response." (PMID 32733437, 2020). "Of particular interest to modulate tumor-specific immune responses are the two PRR, Toll-like receptor 3 (TLR3), which recognizes double stranded RNA and the cytosolic DNA sensor STING." (PMID 32486450, 2020). "A rapid reduction of tumor volume was observed within one day after TLR3/CD40 stimulation in AT-3 and B16 tumor-bearing mice compared to untreated mice." (PMID 33110069, 2020). "For example, treatment of HPV-driven tumors with HPV E7 oncoprotein-derived peptide vaccines combined with TLR3 or TLR9 ligands showed T-cell activation and subsequent tumor regression in vivo." (PMID 33008010, 2020). "ARNAX, a TLR3 agonist, promoted full priming and proliferation of CTLs and enhanced CD8+ T cell infifiltration into the tumor site through TLR3-TIR domain-containing adaptor molecule-1 (TICAM-1)-IRF3-IFN-β axis in DCs." (PMID 33469538, 2020). "In summary, various TLRs can be expressed on numerous cancer cell types and TLR3 and TLR5 appear to be the most promising adjuvants for combining direct anti-tumor properties with immunostimulant effects on APCs and T cells." (PMID 33679703, 2020). "For example, Schau and colleagues developed a system, which was able to deliver dsRNA TLR3 agonist, Riboxxol, specifically to PSCA-positive tumor cells." (PMID 33147700, 2020). "DNA methyltransferase inhibitors have been shown to exert clinical anti-tumor effect by inducing MDA5 and TLR3 signaling pathways." (PMID 33633744, 2020).
tumor (continued). "While Flt3L administration alone would slow tumour growth, combining Flt3L treatment with Poly I:C, a Toll-like receptor 3 (TLR3) ligand, induced a much more dramatic B16 tumour regression." (PMID 31091774, 2019). "The activation of TLR3 and TLR7 triggers Th1 polarization in a tumor through increased IL-12, IL-23, and type I IFN production." (PMID 31083581, 2019). "There is also evidence that stimulation through particular TLRs, such as TLR3 and TLR5, can induce anti-tumour responses and lead to increased tumour cell death." (PMID 29415982, 2018). "Further, HIV-positive J1.1 cell exosomes were unable to enhance proliferation of TLR3-KO HSC3 cancer cells in vitro and xenograft tumor growth in nude mice in vivo." (PMID 30389917, 2018). "It is also suggested that mouse colon carcinoma CT26 cells treated with poly(I:C) can not only induce an immune response, but also induce necrosis toward tumor cells exhibiting increased RIP1 and RIP3 interacting protein by TLR3/TICAM1-reactive oxygen species." (PMID 30127747, 2018). "In the case of TLR3 adjuvant therapy, the acquisition of resistance to CTL activity by tumor cells should be investigated." (PMID 29312355, 2017). "It is likely that DCs internalize tumor cell debris, which contains TAAs, and cross-prime CD8+ T cells via TLR3-mediated activation of DCs." (PMID 29312355, 2017). "In the current study, we show that DC matured in the presence of a combination of IFNγ and ligands for TLR3 (poly I:C), TLR4 (LPS), and TLR8 (R848) display features crucial for triggering efficient T cell-mediated anti-tumor responses." (PMID 28601925, 2017). "G-MDSCs produce reactive oxygen species through the TLR3–TICAM-1 pathway, leading to tumor growth inhibition." (PMID 29312355, 2017). "The target tumor cells were added to BMDMs activated by the following TLR agonists; TLR1/2 agonist Pam3, TLR2/6 agonist LTA, TLR3 agonist poly(I:C), TLR5 agonist flagellin, TLR7 agonist CL264, and TLR9 agonist CpG." (PMID 29123526, 2017). "TLR3 and TLR9 agonists have been shown to enhance iNKT cell’s ability to mature DCs, whereas tumor cells are thought to shed NKG2D ligands in exosomes to block the receptor from recognizing the tumor cell." (PMID 29163518, 2017). "We have demonstrated that the administration of TLR3, TLR4 and TLR21 ligands reduces the incidence of tumours and MDV genome copy numbers in the infected birds." (PMID 27894330, 2016). "TLR3-positive and TUNEL-positive signals were localized to the tumor cell cytoplasm or membrane and to the nucleus, respectively." (PMID 25884709, 2015). "HE staining indicated that there were more monocytes infiltrated in the tumor parenchyma of the EBER expressing tumors compared with the controls in WT group, while in TLR3−/− mice, much less infiltrated monocytes were seen in tumors." (PMID 26172457, 2015). "Both TLR3 and TLR5 are also pro-tumorogenic with their signals mediating tumor invasion and metastasis by enhancing cell migration, but, like TLR4, also have an anti-cancer effect in some situations." (PMID 25309546, 2014). "CC lines significantly increased MFI of TLR-3 and TLR-7 in comparison with the LPS group, whereas, for TLR-9, only tumor cells infected with viruses HeLa and SiHa, induced an increase in MFI (P < 0.05)." (PMID 25309919, 2014). "Future studies will also address downstream effects of TLR3 and IRAK4 alterations on immune/inflammatory responses and tumor behavior using in vitro and in vivo models." (PMID 24194738, 2013). "Double-stranded RNA (dsRNA) activates TLR3 on DCs to release type 1 IFN that induces tumour cell apoptosis and NK-mediated tumour cytotoxicity." (PMID 16892041, 2006). "We examine how TLR3 activation engages interconnected RCD programs, including apoptosis, necroptosis, and immunogenic cell death, and contrast these with pathways driving tumor plasticity and progression." (PMID 42278599, 2026).
tumor (continued). "Our findings revealed a reciprocal negative feedback loop in the regulation of IFN-β signaling, highlighting the role of the TRIM3/TLR3 axis in the suppression of NSCLC progression and offering a promising strategy to suppress tumor growth and enhance immunotherapy efficacy in NSCLC." (PMID 41545343, 2026). "To investigate the co-localization of TLR3 with stem cell markers (ALDH1A1 and CD133) and endogenous ligands (HSP70 and RAGE), we performed immunohistochemical analysis with fluorescently labeled antibodies on seven tumor tissue samples." (PMID 40647457, 2025). "Next, poly(I:C) (which can stimulate TLR3), different CpG ODNs (types A, B, and C), GM‐CSF, Bacillus Calmette–Guérin (BCG), and STING agonists, or their combinations, were co‐encapsulated with tumor antigens into NVs/MVs." (PMID 40574416, 2025). "This suggests that poly(I:C)-induced signaling contributes to immune cell recruitment to ESCC cells via the TLR3/TICAM-1 pathway, though confirming activation of natural killer cells and recruitment of lymphocytes to the tumor microenvironment in ESCC will require further studies." (PMID 40029556, 2025). "By analyzing multiple cohorts validation, we found that patients with higher levels of TLR3 demonstrated significantly improved survival, increased immune infiltration, and higher TMB, positioning TLR3 as a critical immune modulator in the tumor microenvironment." (PMID 40406122, 2025). "Further assessment demonstrated that the expression of necroptosis-related genes, including FADD, MLKL, TLR2, PGAM, HMGB1, CXCL 1, TRAF2, and EZH2, was elevated in tumor tissue, while FAS, RIPK1, RIPK3, TLR3, TNFRSF, ALDH2, and NDRG2 were upregulated in normal intestinal tissues." (PMID 40959081, 2025). "Activation of TLR3/7/8 induces alveolar macrophages to an CD86highCD206lowArg1low M1-like antitumor phenotype, enhancing the expression of T-cell chemokines CXCL10 and CCL5 and effectively suppressing tumor metastasis." (PMID 41293166, 2025). "Activation of NLRP3, TLR3 and TLR4 may lead to chronic inflammation, which contributed to immune evasion and tumor progression." (PMID 40535567, 2025). "Interestingly, survival analysis showed improved outcomes in UCEC patients with high TLR3 expression, whereas results for CESC were inconclusive, reflecting the context-dependent dual role of TLRs in tumor promotion and suppression." (PMID 40847033, 2025). "Taken together, our study uncovers a non-canonical function of nuclear TLR3 to act as an oncogenic protein that drives tumor metastasis and chemoresistance." (PMID 40675966, 2025). "Neither ADU-S100 or Poly I:C, lacking any distracting viral immunogens and both clinically relevant antiviral immune adjuvants triggering the STING/cGAS and TLR3 signaling cascade, respectively, were unable to prime OT-I responses at low-doses despite improved CD8 T cell infiltration into the tumor." (PMID 40166032, 2025). "Additionally, a phase-II trial is ongoing combining nivolumab with BO-112 (polyI:C dsRNA), a Toll-like receptor 3 (TLR3) agonist that has been shown to suppress MDSCs and enhance the T-cell response to the tumor in preclinical settings (NCT04420975)." (PMID 40723291, 2025). "Simultaneously, we found tumor macrophages expressing solely either TLR3, SNCA, or TRAF6 in the tumor-containing lymph, whereas tumor-free lymph macrophages had a significantly higher expression of the combination of these markers, suggesting the presence of the diversified tumor macrophages." (PMID 38719996, 2024). "Therefore, to clarify the role of TLR3 signaling in poly(I:C)-enhanced abscopal effect of radiotherapy, TRL3-knockout mice (Homozygous TLR3-/-) were used to construct HCC subcutaneous tumor model, and further receiving poly(I:C) plus RT treatment." (PMID 38671318, 2024).